CRP (C-reactive protein)
Diseases named in the same sentence as CRP in open-access papers (continued):
Sharing a sentence is not in itself a finding about the gene and the disease.
pneumonia (continued). "C-reactive protein (CRP) and procalcitonin (PCT) have been widely tested for the diagnosis of pneumonia in adults, but few studies have included elderly patients." (PMID 32997689, 2020). "A Cochrane review demonstrated reduced antibiotic prescription with CRP testing, which led to its incorporation in the National Institute for Health and Care Excellence (NICE) guidelines for the diagnosis of pneumonia." (PMID 32070390, 2020). "Increased CEA, Fer, PCT, D2, CRP levels, Neu%, and WBC counts indicate severe pneumonia, while decreased levels indicate treatment effectiveness and disease improvement." (PMID 33537326, 2020). "Procalcitonin (PCT), interleukin-6 (IL-6), C-reactive protein (CRP), sequential organ failure assessment (SOFA) and pneumonia severity index (PSI) scores, and mortality confirmed similar intriguing patterns." (PMID 32689999, 2020). "Patients with preoperative pneumonia had higher WBC (12.10 ± 2.36 vs 9.05 ± 3.22, P < 0.001) and CRP levels (20.46 ± 9.11 vs 12.58 ± 5.45, P < 0.001)." (PMID 33112045, 2020). "The use of the near-patient CRP was often considered an important tool for patients with tonsillitis, and CRP results in patients with LRTI were thought usually to be consistent with the guidelines and diagnoses of acute bronchitis or pneumonia." (PMID 32031035, 2020). "It has been reported that both CRP and ESR had a higher odds ratio in predicting pneumonia than clinical signs alone, and CRP together with clinical signs had adequate sensitivity to estimate the incidence of LRTI." (PMID 33281906, 2020). "A reference diagnosis incorporating the results of CT-scan in all patients was used to assess the accuracy of CRP and PCT in a prospective study of 200 patients (median age 64 years) presenting at the emergency room with suspected pneumonia." (PMID 32997689, 2020). "In a previous study, we showed that there was a strong correlation between the physician’s degree of suspicion of pneumonia and CXR results when the CRP value was known." (PMID 33399009, 2020). "We assessed the accuracy of CRP, PCT, SAA, NP and the ratios CRP/NP and SAA/NP in a prospective observational cohort of elderly patients with suspected pneumonia." (PMID 32997689, 2020). "To minimize the selection bias, we matched severity of pneumonia, LDH, and CRP using propensity scores." (PMID 33330269, 2020). "Although white blood cell count, C-reactive protein (CRP) and erythrocyte sedimentation rate are higher in children with a bacterial aetiology of pneumonia or mixed bacterial–viral aetiology in comparison to viral aetiology, these tests are non-discriminatory." (PMID 31422032, 2019). "Pneumonia patients had significantly higher mean WBC counts (11,334.8 vs. 7515.1 cells/μL, p < 0.001), and CRP levels (98.9 vs. 62.2 mg/L, p = 0.046), but lower mean ALC (1697.9 vs. 2484.7 cells/μL, p = 0.001) compared to non-pneumonia patients." (PMID 31370781, 2019). "The acute-phase protein (C-reactive protein [CRP]) and many inflammatory cytokines (IL-6, IL-8, IL-1α, IL-1β and TNF-α) have been studied in both the sera and pleural effusions of pneumonia patients." (PMID 31215423, 2019). "Of 1554 patients, 263 had chronic kidney disease, demonstrated higher C-reactive protein and SMART-COP scores, and had more multilobar pneumonia, acute kidney injury, ICU admission, and mortality." (PMID 31186488, 2019). "CRP, WCC and ANC were higher in definite bacterial pneumonia and the CRP had value for distinguishing these from presumed viral and other pneumonias." (PMID 30940126, 2019). "We therefore assessed the distribution of inflammatory biomarkers (CRP, WCC and ANC) in blood samples from a prospective case-control study of Western Australian children with radiologically-confirmed pneumonia." (PMID 30940126, 2019).
pneumonia (continued). "Despite antibiotic therapy (amoxicillin + clavulanic acid) fever developed after 6 days with elevated C-reactive protein (CRP) (38 mg/L), and chest radiography showed atelectasis with pneumonia of the right lower lobe." (PMID 31640618, 2019). "Baseline CRP serum levels were also similar (median [IQR], 2.1 [1.0 to 3.7] in participants with pneumonia versus 2.2 [1.0 to 3.8] in controls; p = 0.93)." (PMID 29420547, 2018). "The recorded clinical characteristics include duration of illness, years of smoke, age at onset, gender, and the prevalence of pulmonary heart disease and combined severe pneumonia, WBC count, N%, PCT, CRP, FEV1/predicted, FEV1/FVC." (PMID 29976774, 2018). "The rate of pulmonary complications was the same for children with CRP over 50 mg/l (POCT(Point of Care Testing), part of an adult definition of significant pneumonia) as below 50 mg/l (18% versus 19%, p > 0.05)." (PMID 29698412, 2018). "First, circulating CRP and PCT levels were significant different in the pneumonia patients infected with different pathogens." (PMID 30285748, 2018). "Testosterone levels in males correlated inversely with inflammatory markers (CRP rho = − 0.39, p < 0.001; PCT rho = − 0.34, p < 0.001) and disease severity as assessed by the Pneumonia severity index (PSI) (rho = − 0.23, p = 0.003)." (PMID 30514319, 2018). "Multiple studies have suggested a limited role for inflammatory markers, such as peripheral WBC count, CRP, erythrocyte sedimentation rate, and PCT, in the diagnosis and management of pneumonia in children." (PMID 30425971, 2018). "All four studies showed significantly higher values of CRP and mean white blood cell count (WBC) in the presence of pneumonia." (PMID 30367067, 2018). "Features that differed between the pneumonia and VAP groups from those with brain injuries included markers of infection such as CRP and the higher oxygen requirement, as would be expected." (PMID 30283005, 2018). "Many biomarkers of infection, such as leukocyte count, C-reactive protein (CRP), and procalcitonin have been found to play a role in the early diagnosis and prognosis of pneumonia, especially CAP." (PMID 29710871, 2018). "The authors compared NLR with the Pneumonia Severity Index (PSI) and CURB-65 severity scores, and with infection markers CRP and white blood cell count (WBC)." (PMID 29710871, 2018). "The levels of IL-6, TNF-α, and C-reactive protein were positively correlated with the serum levels of YKL-40, but the IL-10 levels were negatively correlated with YKL-40 levels in all 3 pneumonia subgroups." (PMID 30514252, 2018). "The ROC analysis suggested a cut‐off for CRP of 19 mg/l to differentiate between children with and without signs of bacterial infection, for example positive urine/blood culture or IMCI pneumonia, but the area under the curve (AUC) was low at only 0.62." (PMID 27935664, 2017). "It was a 2 year old boy with a double sided pneumonia, DSS 19, maximum CRP 51 mg/ml, treated with intravenous antibiotics for 7 days." (PMID 28077074, 2017). "In Europe, CRP > 20 mg/L is recommended by the National Institute for Health and Care Excellence (NICE) Pneumonia guidelines as a trigger for prescribing antibiotics." (PMID 28991170, 2017). "Pneumonia diagnosis, comorbidities expressed through Cumulative Illness Rating Scale (CIRS), setting of living, length of stay, serum hs-CRP and procalcitonin at admission were collected for each patient." (PMID 26772604, 2016). "Point-of-care (POC) C reactive protein (CRP) is incorporated in National Institute of Health and Care Excellence (NICE) guidelines for the diagnosis of pneumonia, reduces antibiotic prescribing and is cost effective." (PMID 26940107, 2016). "Although CRP elevation has also been noted in HF patients, the prediction rate of the differentiating ability between ADHF and ADHF with superimposed pneumonia (AUC 0.918) was good compared with common practice clinical and radiological criteria." (PMID 27682424, 2016).
pneumonia (continued). "The areas under the ROC curves for initial DNI, CRP, and WBC for differentiating the ADHF group from the ADHF with pneumonia group were 0.916 (95% confidence intervals [CI] 0.859–0.955), 0.828 (95% CI 0.756–0.886), and 0.715 (95% CI 0.635–0.786), respectively." (PMID 27682424, 2016). "The initial DNI’s ability of prediction for ADHF with superimposed pneumonia in the ED was good and it was better than those of serum WBC and CRP." (PMID 27682424, 2016). "These abnormal CRP responses are considered to be a predictor for incisional SSI in general surgery such as colorectal surgery, if pneumonia or anastomotic leakage are unlikely or excluded." (PMID 25888882, 2015). "Inflammatory proteins C-reactive protein (CRP) and procalcitonin (PCT) have been evaluated as markers of radiological pneumonia, mostly in adults; results have been variable." (PMID 26366571, 2015). "In that study mean levels of copeptin, CRP and number of leukocytes in blood in patients with UTI were similar to those with pneumonia and other infections with the exception of procalcitonin level that was lower in the former." (PMID 26152182, 2015). "The combination of a high CRP and neutrophil count had good specificity in determining PEP on CXR but a low sensitivity, making it an unsuitable test to diagnose pneumonia." (PMID 23320118, 2013). "We defined two batches of the three parameters with highest AUC values for any infection, pneumonia, UTI and OI by combining WBC, CRP and copeptin (batch 1) as well as WBC, CRP and PCT (batch 2)." (PMID 23118979, 2012). "Pneumonia severity (CURB-65 score), clinical characteristics, complications and outcomes were related to the NLCR and compared with C-reactive protein (CRP), neutrophil count, white blood cell (WBC) count." (PMID 23049706, 2012). "PLT and PCT values were higher, while CRP, ESR and WBC values were lower in PTB than in the pneumonia group." (PMID 23114411, 2012). "The combination of the biomarkers WBC, CRP and copeptin (AUC: 0.92) and WBC, CRP and PCT (AUC: 0.90) showed a better predictive accuracy concerning the development of pneumonia during hospitalization compared to each marker by itself (p-Wald <0.0001)." (PMID 23118979, 2012). "WBC, CRP, copeptin and PCT were all independent predictors of any infection, pneumonia and UTI developed at least 24 hours after measurements." (PMID 23118979, 2012). "Batch 2 (WBC, CRP, PCT) better predicted any infection (Wald-p<0.001), pneumonia (Wald-p<0.001) and UTI (Wald-p = 0.014) than the best single predictor alone." (PMID 23118979, 2012). "In our study, PLT, PCT, WBC, CRP and ESR values were significantly higher both in PTB and pneumonia groups than in healthy controls." (PMID 23114411, 2012). "Among the three age groups, the oldest children showed the longest duration of fever, highest C-reactive protein (CRP) values, and the most severe pneumonia pattern." (PMID 20604923, 2010). "CRP and ESR were significantly higher in the patients with pneumococcal or aetiologically undefined pneumonia than in those with influenza A pneumonia." (PMID 16433910, 2006). "In addition, all patients with pneumonia had serum PCT levels > 0.5 ng/mL and/or CRP levels > 20 mg/dL." (PMID 41557164, 2026). "Also, the diagnosis of pneumonia in TBI patients is challenging since fever and leukocytosis are common in them, and TH reduces the leukocyte count and C-reactive protein levels." (PMID 41136964, 2025). "This suggests that PLT and CRP expression may influence the occurrence of ACD, with CRP, PCT, and IL-6 being particularly significant factors contributing to ACD in children with severe pneumonia." (PMID 41234411, 2025). "The patient was started on prophylactic antimicrobial therapy for recurrent skin abscesses, lymphadenitis, and pneumonia without CRP elevation." (PMID 40526438, 2025). "These included EVD, pneumonia, tracheotomy, and PCT, CRP, and Alb levels." (PMID 40529435, 2025).
pneumonia (continued). "Other markers, such as the CRP/albumin ratio, neutrophil-to-lymphocyte ratio (NLR), and platelet-to-lymphocyte ratio (PLR), have been assessed in pneumonia research, although data regarding their clinical utility in predicting disease progression remain limited." (PMID 41018059, 2025). "The high CRP level in our patient was due to pneumonia, highlighting that elevated CRP should not immediately direct suspicion toward SCAD complications when another infectious or inflammatory process is present." (PMID 40821280, 2025). "While the pneumonia and no complication groups also demonstrated lower CRP levels, the pneumonia group exhibited a trend toward a second peak at day 7 posttrauma, without significant differences from the other cohorts." (PMID 40367515, 2025). "Based on these findings, an ROC curve was constructed, demonstrating that the combined prediction of mechanical ventilation, CRP, PCT, IL-6, and IgA for ACD in children with severe pneumonia achieved an AUC of 0.882, significantly higher than the AUC of any single indicator (P < 0.05)." (PMID 41234411, 2025). "Pulmonary embolism was unlikely (low Geneva score 3; Wells 0; normal D‐dimer), and pneumonia was improbable (no fever/cough; low C-reactive protein (CRP))." (PMID 41340971, 2025). "proGRP and CRP were the variables that made difference between ADC/SQCC and pneumonia/COPD groups." (PMID 39703761, 2025). "These patients were statistically older (p < 0.001), had higher concentrations of CRP (p < 0.001), IL-6 (p < 0.001), and D-dimer (p < 0.001), and exhibited lower concentrations of hemoglobin (p = 0.006) compared to those without pneumonia." (PMID 40969806, 2025). "The examined CRP changes are found to correlate with the observable degree of pneumonia; however, they do not correspond to the changes visible in chest X-rays." (PMID 39064460, 2024). "The correlation between white blood cells, percentage, C-reactive protein, and pneumonia was stronger, while albumin showed a negative correlation with pneumonia." (PMID 39398953, 2024). "In the current study, CRP levels in patients who developed pneumonia tended to be higher than those in patients who did not." (PMID 38525743, 2024). "The levels of IL-6, CXCL10, LD, and CRP were significantly higher in patients with pneumonia than in those without pneumonia, both in the vaccinated and the unvaccinated group." (PMID 38694512, 2024). "After conducting LD analyses and eliminating confounding variables, the ultimate counts of IVs for CRP, SAA1, IL-6, TNF-α, WBC, GlycA, GI, dysentery, pneumonia, BP, BLA, PP, and UTI are 1,594, 1,959, 1,021, 1,911, 1,597, 1,871, 1,870, 1,965, 1,876, 1,875, 1,864, 1,877, and 1,888, respectively." (PMID 38585702, 2024). "Draw ROC curves for predicting pneumonia in children with NSE, ESR, and CRP in the control group." (PMID 38822291, 2024). "Previous studies have confirmed that CRP, a non-specific systemic inflammatory response protein, reflects the severity of acute temporal pneumonia and extrapulmonary tissue damage." (PMID 38655275, 2024). "CRP, PCT, and WBC count were utilized to identify pneumonia patients." (PMID 38910264, 2024). "Additionally, the obvious decrease trends of three bacterial infectious biomarkers, c‐reactive protein (CRP), serum amyloid A (SAA) and procalcitonin (PCT) were observed after treatment in M‐MFL@MB groups, reflecting the pneumonia control after therapy." (PMID 37933983, 2024). "Data was collected through a structured questionnaire, including demographic information and clinical categorization of pneumonia severity using WHO criteria, SpO2 levels, chest X-rays, complete blood count (CBC), and C-reactive protein (CRP) levels obtained within 24 hours of admission." (PMID 38449934, 2024). "Similarly, patients with mild or moderate illness, and individuals with severe pneumonia, ARDS, or multiorgan failure typically have significantly higher CRP levels." (PMID 39641395, 2024).
pneumonia (continued). "The use of biomarker tests, such as (procalcitonin) PCT or (c-reactive protein) CRP, for diagnosing and monitoring pneumonia has been suggested, although most studies have not been specifically conducted in immunocompromised individuals." (PMID 37892664, 2023). "Spearman’s analysis revealed a significant positive correlation between pneumonia and neutrophile, interleukin-6 IL-6, C-reactive protein CRP (p = 0.01, p < 0.001, p < 0.001), negative to lymphocyte count (p < 0.001)." (PMID 37608339, 2023). "In human medicine, CRP concentrations have been correlated with the severity of pneumonia, but there are no publications demonstrating a correlation with the presence or type of parapneumonic effusion." (PMID 37008361, 2023). "When comparing hospitalized pneumonia patients with non-hospitalized patients, plasma CRP level (p < 0.001) and platelet (p = 0.006) and eosinophil (p = 0.032) counts showed statistically significant differences." (PMID 37570378, 2023). "The highest CRP values due to infections are recorded in patients with pneumonia, and the highest CRP values in non-infectious inflammatory diseases are recorded in patients with inflammatory bowel disease." (PMID 36865442, 2023). "Thus, elevated values of CRP, ferritin, bilirubin, fibrinogen, AST, and ALT can be good predictors of pneumonia in patients with SARS CoV-2." (PMID 36836416, 2023). "The change of serum CRP level after PEG can predict peristomal wound infection and pneumonia." (PMID 37189057, 2023). "Full blood count and C-reactive protein (CRP) cannot differentiate between bacterial and viral infection in hospitalised children, so these investigations are potentially over-utilised for pneumonia diagnosis." (PMID 37425493, 2023). "The patients who developed pneumonitis and pneumonia had significantly higher CRP levels after CRT than those who did not develop pneumonitis or pneumonia (p-value = 0.01 and p-value < 0.001)." (PMID 37476372, 2023). "Pneumonia can be present in ED patients without respiratory symptoms or signs who have a fever, hypothermia, and/or elevated CRP." (PMID 37115214, 2023). "In this analysis of the OPTIMACT trial, we observed that pneumonia can occur in patients with fever or elevated CRP even if they do not show respiratory signs or symptoms." (PMID 37115214, 2023). "Analysis of the general health and biochemical data according to pneumonia revealed a significant correlation with neutrophile, IL-6, CRP levels (p = 0.01, p < 0.001, p < 0.001), as was found negative between pneumonia and lymphocytes (p < 0.001)." (PMID 37608339, 2023). "This register-based study showed that every other patient with acute bronchitis or pneumonia and negative imaging received antibiotics despite low median CRP values." (PMID 37508261, 2023). "• Clinical significant pneumonia does occur in patients who have a fever, low core body temperature, or elevated CRP without respiratory symptoms or signs." (PMID 37115214, 2023). "CRP levels were not statistically different between patients with pneumonia/ARDS compared to patients with other types of infection." (PMID 37296737, 2023). "In addition, changes in CRP, PCT, WBC, IL-6, Clostridium difficile toxin, and PSI pneumonia scores were assessed." (PMID 38050216, 2023). "Age, CRP (p ≤ 0.001) and neutrophils (p = 0.031) were significantly higher in the group of patients with pneumonia compared to patients without pneumonia." (PMID 37570378, 2023). "This register-based study showed that every other patient with acute bronchitis or pneumonia and negative chest imaging received antibiotics despite low median CRP values." (PMID 37508261, 2023). "Serum procalcitonin (PCT) and CRP have been shown to predict positive blood culture among children with severe pneumonia, though that does not rule out infection in malnourished children." (PMID 37542670, 2023).